NLRP3 (NLR family pyrin domain containing 3)
Diseases named in the same sentence as NLRP3 in open-access papers (continued):
Sharing a sentence is not in itself a finding about the gene and the disease.
lung carcinoma (121 papers, 2016 to 2026). "This study utilized immunoinformatics and structural bioinformatics approaches to design and evaluate a multi-epitope vaccine targeting pyroptosis-associated antigens (CARD8, NAIP, NLRP1, and NLRP3), which are implicated in lung cancer immunology." (PMID 41857073, 2026). "For example, studies in the model of lung cancer found that Nr1d1 deficiency promoted tumorigenesis by increasing NLRP3 inflammasome activation and pro-inflammatory cytokine production, potentially mediated in part through the downregulation of NRF2." (PMID 39199147, 2024). "In conclusion, we showed that NR1D1 deficiency in the TME promotes lung cancer development and metastatic potential through NLRP3 inflammasome activation." (PMID 37524704, 2023). "In the present study, we found that the activation of the NLRP3 inflammasome in the NR1D1-deficient TME plays a crucial role in lung cancer development and EMT." (PMID 37524704, 2023). "The mechanism underlying the anti-lung cancer effects of these two components was found to be related to the regulation of protein expression in the NLRP3 inflammasome pathway." (PMID 37907950, 2023). "Given the complex role of NLRP 3 inflammasome in the initiation and progression of neoplasia, the NLRP3 inflammasome and its associated pathways represent promising therapeutic targets for the prevention and treatment of lung cancer." (PMID 38026959, 2023). "In a separate study, alum and crystalline silica, the causal agent for silicosis and lung cancer, were shown to activate the NLRP3 inflammasome by disrupting the lysosome to release cathepsin B, which serves as a sterile DAMP for NLRP3 activation." (PMID 36669831, 2023). "To explore the role of NLRP3 inflammasome responses in lung cancer with Qi-yin deficiency, we first detected the serum levels of IL-1β and IL-18." (PMID 35292015, 2022). "Expectedly, in the present study, we found that BFXJY treatment relieved the up-regulation of NLRP3 inflammasome responses in lung cancer with Qi-yin deficiency, as indicated by the decrease of the serum, mRNA, and protein level of NLRP3, ASC, IL-1β, MDA." (PMID 35292015, 2022). "Cordyceps acid diminished lung cancer development in nude mice which was associated with the inhibition of the Nrf-2/HO-1/NLRP3/NF-κB pathway in tumor tissue." (PMID 35890166, 2022). "Then, we estimated the protection effect of BFXJY on lung cancer mice with Qi-yin deficiency, through deterring tumor growth, NLRP3 inflammasome, PKC signaling, and homeostasis of gut microbiota." (PMID 35292015, 2022). "BuFeiXiaoJiYin ameliorates the NLRP3 inflammation response and gut microbiota in mice with lung cancer companied with Qi-yin deficiency." (PMID 35292015, 2022). "It was also reported that NLRP3 inflammasome activity was closely associated with tumor progression in lung cancer." (PMID 35652821, 2022). "Taken together, these findings suggested that BFXJY treatment inhibited NLRP3 inflammasome activation in lung cancer with Qi-yin deficiency." (PMID 35292015, 2022). "For instance, NLRP3 acts as a tumor suppressor in lung cancer; genetic variations in NLRP3 genes determine the susceptibility to the Human papillomavirus and also affect cervical cancer progression." (PMID 32604771, 2020). "Genetic polymorphisms involved with the NLRP3 inflammasome were linked to various diseases, such as rheumatoid arthritis, ankylosing spondylitis, melanoma, liver cancer, lung cancer, and ovarian cancer." (PMID 30211233, 2018). "Furthermore, NLRP3 activation has been associated with promoting the proliferation and migration of lung cancer cells, impacting cancer cell viability and survival." (PMID 39769450, 2024). "Further supporting these findings, lung cancer cells incubated with conditioned media from BMAL1-deficient CAMs showed augmented NLRP3 inflammasome activation, driving cancer cell proliferation, consisting to the effects that observed in breast cancer with BMAL1 knockdown." (PMID 38607733, 2024).
lung carcinoma (continued). "The role of NLRP3 in lung cancer is not clearly known; further studies are needed to elucidate the mechanisms underlying NLRP3 inflammasome’s beneficial and harmful impacts on lung cancer pathophysiology." (PMID 39769450, 2024). "Exposure to respirable particulate matter such as asbestos may activate pyrin domain-containing protein 3 (NLRP3) inflammasome and increase the risk of malignant mesothelioma and lung cancer." (PMID 35036439, 2022). "However, the relationship between gut microbiota and NLRP3 inflammasome responses in lung cancer with Qi-yin deficiency remains elusive." (PMID 35292015, 2022). "In conclusion, our results demonstrated that NLRP3 inflammasome responses were upregulated in lung cancer with Qi-yin deficiency, which could be relieved with BFXJY treatment." (PMID 35292015, 2022). "In the present study, we have demonstrated that NLRP3 inflammasome responses were upregulated in lung cancer with Qi-yin deficiency, which could be relieved with BFXJY treatment." (PMID 35292015, 2022). "NLRP3 inflammasome responses and gut microbiota have been shown an important role in lung cancer, however, the relationship between gut microbiota and NLRP3 inflammasome responses in lung cancer with Qi-yin deficiency remains elusive." (PMID 35292015, 2022). "In this study, we found that BFXJY could inhibit the tumor growth in lung cancer with Qi-yin deficiency by reducing the production of IL-1β and IL-18 and inhibiting NLRP3 inflammasome activation, which might be associated with the inhibition of PKC signaling." (PMID 35292015, 2022). "Therefore, in the present study, we reported that BFXJY can alleviate NLRP3 inflammasome responses and regulate dysbiosis in lung cancer with Qi-yin deficiency in vivo." (PMID 35292015, 2022). "However, the role of NLRP3 inflammasome in lung cancer with Qi-yin deficiency still needs more attention." (PMID 35292015, 2022). "Therefore, in lung cancer with Qi-yin deficiency, IL-1β and other interleukin pro-inflammatory factors are expressed in large quantities, which are also the main products of NLRP3 inflammasomes." (PMID 35292015, 2022). "This suggests that NLRP3 is involved in α5-nAChR-mediated lung cancer progression and provides a new molecular mechanism for targeting the α5-nAChR/STAT3/NLRP3 axis against lung cancer." (PMID 40143965, 2025). "This silencing activates key pro-metastatic cascades like NF-κB/NLRP3 inflammasome hyperactivation, ultimately driving lung cancer dissemination." (PMID 41409273, 2025). "The regulation of STAT3 by α5-nAChR serves as a mediator in modulating the expression levels of NLRP3, thereby affecting the progression of lung cancer." (PMID 40143965, 2025). "The inflammatory response of lung cancer cells via the NLRP3 inflammasome pathway is known to enhance cancer cell migration and invasion." (PMID 39858497, 2025). "Tumor-derived exosomal TRIM59 reprograms macrophages toward a tumor-promoting phenotype by inducing the proteasomal degradation of ABHD5, thereby activating the NLRP3 and enhancing lung cancer progression through increased IL-1β secretion." (PMID 40443670, 2025). "(2020) showed that lung cancer cells release exosomes containing TRIM59, an E3 ligase, which are transferred to macrophages, leading to NLRP3 inflammasome activation and promoting lung cancer progression." (PMID 40692785, 2025). "This process involves both H3K27me3 mediated transcriptional silencing and m6A-dependent mRNA decay, effectively inhibiting NLRP3 dependent pyroptosis and thereby facilitating drug resistance in lung cancer." (PMID 41409273, 2025). "Glyburide reduced tumor proliferation in bladder and lung carcinoma by modulating the cell cycle and inhibiting the NLR family pyrin domain containing 3 (NLRP3) inflammasome." (PMID 40227837, 2025). "For instance, a recent study found that LncRNA LINC00969 promotes acquired gefitinib resistance in lung cancer by epigenetically suppressing NLRP3, thereby inhibiting pyroptosis." (PMID 40933997, 2025).
lung carcinoma (continued). "The NLRP3 inflammasome, a key player in inflammatory responses, tends to be overactive in specific types of cancer, such as liver and lung cancers." (PMID 40008397, 2025). "TRIM59 promotes lung cancer progression by regulating autophagy or the NLRP3 inflammasome signalling pathway." (PMID 38291200, 2024). "Several studies indicate that lung cancer chemopreventive effects of some of the antioxidants are mediated by inhibiting NLRP3 inflammasome." (PMID 39769450, 2024). "A recent study demonstrated that tumor-derived exosomal TRIM59 activates NLRP3 inflammasomes in macrophages and promotes their pro-tumor M2 polarization, thereby promoting lung cancer progression." (PMID 39494337, 2024). "ANGPTL4 is known to promote gefitinib resistance in lung cancer by regulating the NLRP3/ASC/Caspase 8 pathway." (PMID 38731835, 2024). "Studies have shown that USP5 can deubiquitinate Forkhead Box M 1 (FoxM1) and NLR family pyrin domain containing 3 (NLRP3), which promotes the growth of pancreatic ductal adenocarcinoma and non‐small cell lung cancers and reduce inflammation." (PMID 39189428, 2024). "The results demonstrated that treatment of lung cancer A549 cells with LPS and ATP induced the expression of IL-6 and inflammasome-related cytokines IL-1β and IL-18, as well as increased NLRP3 gene expression." (PMID 38026959, 2023). "Conversely, NLRP3 inflammasome activation can also facilitate lung cancer development and progression by inducing chronic inflammation, angiogenesis, invasion and metastasis." (PMID 37715239, 2023). "Emerging evidence supports the pivotal role of aberrantly activated inflammasomes, including NLRP3 (nucleotide-binding oligomerization domain, leucine-rich repeat and pyrin domain-containing protein 3), in lung cancer pathogenesis." (PMID 37528154, 2023). "Inflammatory response of lung cancer cells through the NLRP3 inflammasome pathway not only promotes cancer cell growth but also enhances cancer cell invasion and metastasis." (PMID 38026959, 2023). "It was reported that under the stimulation of IL‐17A, the process of migration, invasion, and EMT can be promoted by NLRP3 activation in lung cancer." (PMID 37062076, 2023). "In conclusion, KAE and PLA, two active components of A. acutiloba flower extract, had significant anti-lung cancer activities exerted through regulation of proteins related to the NLRP3 inflammasome pathway." (PMID 37907950, 2023). "In the context of the NLRP3 inflammasome pathway, which plays a crucial role in the inflammatory response of lung cancer cells, we have expanded upon the mechanisms discussed in the references." (PMID 38026959, 2023). "Treatment with MCC950, a specific inhibitor of NLRP3 inflammasome, blocked tumorigenesis in NR1D1-deficient mice in an orthotopic lung cancer model." (PMID 37524704, 2023). "Our study emphasizes the importance of major inflammatory mediators in lung cancer growth and identified the activation of the NLRP3 inflammasome as an important mechanism and potential therapeutic target for cancer treatment." (PMID 37528154, 2023). "SE-EA extract and its active compounds, EGF-A and EGF-B can effectively suppress the invasion of A549 lung cancer cells stimulated by LPS-ATP via the NLRP3 inflammasome pathway." (PMID 38026959, 2023). "Consistent with our results, it was reported that NLRP3 inflammasome activation in macrophages facilitates lung cancer progression and migration." (PMID 37524704, 2023). "Our findings suggest that SE-EA extract and its active compounds, EGF-A and EGF-B, possess potential anti-cancer properties as they inhibit the invasion of A549 lung cancer cells stimulated by LPS and ATP via the NLRP3 inflammasome pathway." (PMID 38026959, 2023). "In the context of our study, we align with these recent findings, as we have observed that NLRP3 activation contributes to the progression of cancer cells in A549 lung cancer cells." (PMID 38026959, 2023).
lung carcinoma (continued). "NLRP3 inflammasome has anti-cancer effects on colon cancer and pro-cancer effects on gastric cancer and lung cancer." (PMID 36276078, 2022). "For example, lung cancer microparticles (L-MPs) activated TLR3 and NLRP3 inflammasome, induced macrophages to release IL-1β, and thus promoted lung cancer development." (PMID 35413927, 2022). "In oral squamous carcinoma NLRP3 activation promotes 5-Fluorouracil resistance “in vitro” and “in vivo”; and NLRP3 inflammasome has been detected in cisplatin-resistant lung cancer cell lines." (PMID 35530309, 2022). "Previous studies have also found that NLRP3 enhances the proliferation and migration of A549 lung cancer cells." (PMID 36349316, 2022). "It was found that after blocking NLRP3, the effects above after IL-17A stimulation was weakened, confirming that IL-17A can promote the migration, invasion and the EMT process of lung cancer cells by activating NLRP3 in vitro." (PMID 36349316, 2022). "Previously, we identified that NLRP3 activation was low in the lung cancer cell line, A549, whilst it was high in the prostate cancer cell line, PC3." (PMID 36012769, 2022). "Although the A549 cell line is a lung cancer-derived cell line, it has a proper NLRP3 inflammasome activation and pro-inflammatory response in reaction to the stimulation of LPS and pathogenic stimulations." (PMID 35777914, 2022). "In this study, we aimed to select the miRNAs targeting NLRP3 from TargetScan and miRDB Online Database and finally choose the most suitable miRNA for the further experiments due to the expression in lung cancer cells." (PMID 36276078, 2022). "Lung cancer-derived EVs induce NLRP3 activation in macrophages, thus providing a positive feedback loop to promote cancer progression via IL-1β secretion in mice." (PMID 35530309, 2022). "Tumor-derived exosomal TRIM59 induces the tumor-promoting function of macrophages to activate the NLRP3 inflammasome signaling pathway, thereby promoting lung cancer progression." (PMID 36118863, 2022). "The malignancy of lung cancer cells was reduced after PD treatments via targeting caspase 3, arresting cancer cells at the S phase and inhibiting NLRP3 inflammasome by downregulation of the NF-κB pathway." (PMID 36364001, 2022). "NLRP3 was found up-regulated in various forms of cancer such as lung cancer, lymphoma, oral squamous cell carcinoma etc., indicating its potential role in the adjuvant diagnostic index." (PMID 33821998, 2021). "We herein report the ability of SAL to suppress the proliferation and migration of human lung cancer cells through AMPK-dependent NLRP3 inflammasome regulation." (PMID 34457117, 2021). "In summary, these results indicate that SAL suppresses the proliferation and migration of human lung cancer cells through AMPK-dependent NLRP3 inflammasome regulation." (PMID 34457117, 2021). "GPRC5A also prevents acute lung injury and lung cancer and is mainly expressed in distal, flat bronchiolar epithelium, which also express NLRP3." (PMID 32778128, 2020). "They observed that polydatin repressed the proliferation of lung cancer cells, evolution of lung cancer through inhibition of the NLRP3 inflammasome signaling pathway, and downregulated the activation of the NF-κB signaling pathway." (PMID 33015196, 2020). "In this view, we aimed to investigate a central innate immune response pathway, the NLRP3 inflammasome, in lung cancer PBMCs and AMs, in order to gain insight on inflammatory processes related to LC." (PMID 30365491, 2018). "Our primary finding, that alveolar macrophages show decreased transcriptional and secretional TLR4 mediated NLRP3 activation markers, suggests that in human lung cancer innate immune responses in alveolar macrophages are compromised." (PMID 30365491, 2018). "We thus investigated the NLRP3 pathway in Bronchoalveolar Lavage derived alveolar macrophages and peripheral blood leukocytes from patients with primary lung cancer and healthy individuals." (PMID 30365491, 2018).
lung carcinoma (continued). "The effect of lentinan on NLRP3 inflammasome activation has been previously studied, whereas the previous study used human lung cancer cell lines, A549, instead of macrophages or dendritic cells." (PMID 28465544, 2017). "NLRP3 inflammasome components IL-1β and IL-18 were found to be highly expressed in lung cancer cell lines and tissues than in cancer-adjacent normal tissues." (PMID 28865486, 2017). "Recent evidence showed that overexpressed and constitutively activated NLRP3 inflammasome contributed to the progression of human melanoma cells, lung cancer cells, and colon cancer cells." (PMID 28865486, 2017). "Similarly, in lung cancer, cytokines have a significant impact on cancer prognosis, such as the upregulation of IL-17A in the lung tumor-induced overexpression of NLRP3 and the enhanced lung tumor invasiveness ability mediated by the EMT." (PMID 39941895, 2025). "Recently, research demonstrated that TRIM38 interacts with GLUT1 to suppress the progression of bladder cancer, and another study revealed that TRIM38 regulates the AMPK/NF‐κB/NLRP3 pathway to inhibit the progression of lung cancer, gradually revealing the importance of TRIM38 in malignancy." (PMID 40047371, 2025). "In cancer, tumor‐derived exosomal TRIM59 could convert macrophages to a pro‐tumor phenotype via regulating ABHD5 proteasomal degradation, and led to NLRP3 inflammasome activation to promote lung cancer progression." (PMID 40135589, 2025). "The selective NLRP3 inhibitor RRx-001 is currently in Phase III trial for lung cancer, and may have potential for neurodegenerative diseases treatment." (PMID 41280719, 2025). "Mechanistically, the lung cancer-promoting effect of HDM was primarily attributed to the chronic activation of the Nod-like receptor family pyrin domain-containing protein 3 (NLRP3) inflammasome in lung macrophages, leading to persistent IL-1β production in the lungs." (PMID 41445736, 2025). "However, in AMs of lung cancer patients, NLRP3 inflammasome activation is decreased, and IL-1β secretion is decreased." (PMID 39420831, 2024). "Although the effect of Sch B on IL-1β has seldomly been observed in cancer models, its inhibitory effect on nuclear factor kappa-light-chain-enhancer of activated B cells (NF-ĸB), the central mediator of the priming signal of NLRP3 inflammasome, has been investigated in lung cancer cell lines." (PMID 38254674, 2024). "Additionally, the expression of NFkB stimulated Nlrp3 gene expression to establish lung cancer inflammation." (PMID 38279220, 2024). "In agreement, previous reports have indicated that ATP stimulation of alveolar macrophages, derived from both IPF and lung cancer patients, led exclusively to an elevation in IL-18 levels, which was explained by an impaired NLRP3 inflammasome and a defective autophagy in IPF patients." (PMID 38300690, 2024). "Conversely, some studies suggest a protective role of NLRP3 in lung cancer." (PMID 39769450, 2024). "Although the NLRP3 inflammasome appears to have both pro- and anti-tumorigenic effects in a context-dependent and tissue-specific manner, several experimental studies have reported that it enhances lung cancer progression." (PMID 37528154, 2023). "An increasing body of evidence indicates that the NLRP3 inflammasome plays a pivotal role in the development and progression of various types of cancer, including gastrointestinal cancer, skin cancer, breast cancer, hepatocellular carcinoma, and lung cancer." (PMID 38026959, 2023). "Therefore, it can be concluded that the inflammatory response triggered by LPS-ATP via the NLRP3 inflammasome pathway enhances the invasive capability of A549 lung cancer cells." (PMID 38026959, 2023). "Targeting NLRP3 inflammasome or its downstream mediators may have therapeutic potential for LCE patients with lung cancer, but it requires careful consideration of the balance between inflammation and immunity." (PMID 37715239, 2023).